LAT (linker for activation of T cells)
Description:
Required for TCR (T-cell antigen receptor)- and pre-TCR-mediated signaling, both in mature T-cells and during their development. Involved in FCGR3 (low affinity immunoglobulin gamma Fc region receptor III)-mediated signaling in natural killer cells and FCER1 (high affinity immunoglobulin epsilon receptor)-mediated signaling in mast cells. Couples activation of these receptors and their associated kinases with distal intracellular events such as mobilization of intracellular calcium stores, PKC activation, MAPK activation or cytoskeletal reorganization through the recruitment of PLCG1, GRB2, GRAP2, and other signaling molecules.
Synonyms: pp36; LAT1; IMD52
Tractability: Antibody: UniProt places it where antibodies can reach, with high confidence; its Gene Ontology location is reachable by antibodies, with high confidence; UniProt predicts a signal peptide or a membrane-spanning region; the Human Protein Atlas places it where antibodies can reach. PROTAC: UniProt records ubiquitination sites on it; ubiquitination databases record sites on it; its protein half-life has been measured.
Target class: Other membrane protein
Gene: Protein-coding gene on chromosome 16 (28,984,808 to 28,990,784, forward strand). Ensembl gene ENSG00000213658.
Subcellular location: Cell membrane
Subcellular location (Human Protein Atlas): Plasma membrane; Golgi apparatus
Pathways (Reactome):
Immune System: DAP12 signaling; FCERI mediated Ca+2 mobilization; FCERI mediated MAPK activation; Fc epsilon receptor (FCERI) signaling; Generation of second messenger molecules
Hemostasis: GPVI-mediated activation cascade
Signal Transduction: RAF/MAP kinase cascade
Gene Ontology:
Molecular function: protein binding; protein kinase binding; signaling adaptor activity; signaling receptor complex adaptor activity
Biological process: calcium-mediated signaling; immune response; integrin-mediated signaling pathway; intracellular signal transduction; positive regulation of MAPK cascade; positive regulation of protein kinase activity; Ras protein signal transduction; regulation of T cell activation; T cell activation; T cell receptor signaling pathway; inflammatory response; signal transduction
Cellular component: immunological synapse; membrane; plasma membrane; COP9 signalosome; membrane raft; TCR signalosome; cell-cell junction
Genetic constraint (gnomAD): Loss-of-function variants: 12 observed, 41.01 expected, observed/expected ratio (o/e) 0.29, 90% interval 0.19 to 0.47. The upper end of that interval is the gene's LOEUF score, 0.47, which puts it in group 2 of 6, group 1 being the genes least tolerant of losing a copy. Missense variants: 253 observed, 317.5 expected, observed/expected ratio (o/e) 0.8, 90% interval 0.72 to 0.88. Synonymous variants: 117 observed, 126.87 expected, observed/expected ratio (o/e) 0.92, 90% interval 0.79 to 1.08.
Gene-disease validity (ClinGen):
ClinGen rates the evidence that LAT causes each of these diseases.
severe combined immunodeficiency due to LAT deficiency (autosomal recessive): Definitive.
Homologues: Orthologues: chimpanzee LAT (99% identical), dog LAT (75% identical), pig LAT (75% identical), mouse Lat (69% identical), rat Lat (68% identical), guinea pig LAT (66% identical), rabbit LAT (65% identical), macaque LAT (62% identical).
Diseases named in the same sentence as LAT in open-access papers:
LAT is named in the same sentence as 81 diseases in open-access papers, as found by Europe PMC text mining. Sharing a sentence is not in itself a finding about the gene and the disease. The quoted sentences say what the papers report.
Immunodeficiency (15 papers, 2013 to 2025). Failure of the immune system to protect the body adequately from infection, due to the absence or insufficiency of some component process or substance. "WES in our patient also revealed the presence of a variant in the LAT gene, whose protein product is associated with AR early-onset immunodeficiency with autoimmunity." (PMID 40686918, 2025). "In this regard, a family has been described in which mutations in LAT resulting in the generation of a premature stop-codon and protein truncation leads to a novel form of severe combined immunodeficiency." (PMID 37759563, 2023). "We posit that the dysregulated TCR signaling due to the LAT mutations can result in a spectrum of disease phenotypes from immune deficiency to autoimmunity depending on compensatory signaling mechanisms and additional environmental triggers." (PMID 34923645, 2022). "In some patients, the LAT mutation resulted in immunodeficiency, while in others it led to autoimmune disease." (PMID 34923645, 2022). "The described kindred with a homozygous mutation in LAT manifested a progressive combined immunodeficiency and profound immune dysregulation." (PMID 34868246, 2021). "In humans, mutations or polymorphisms in LAT recapitulate the range of mouse phenotypes ranging from autoimmunity to immunodeficiency." (PMID 34012443, 2021). "Loss of the cytoplasmic tail of LAT due to a mutation in exon 5 resulted in immunodeficiency characterized by a decrease in circulating T cells, but simultaneous severe autoimmunity." (PMID 34012443, 2021). "The CD19 and LAT genes are associated with immunodeficiency." (PMID 39039444, 2024). "Interestingly, similar to the hypomorphic ZAP70 mutations that can lead to immunodeficiency and/or autoimmunity in humans, a second study of LAT mutations presents a more complicated phenotype with some unexpected clinical and immunologic features." (PMID 34923645, 2022). "Moreover, a human immunodeficiency has been described in which a loss-of-function mutation of LAT generated strongly reduced numbers of T cells, with abolished Erk signaling." (PMID 33562083, 2021). "Altogether, these results show that the phosphorylation of LAT at Y136 constitutes an important step for the kinetic-proofreading model, which requires the proper conditions, as both signaling deficiency and hyperactivity can lead to immunodeficiency and/or autoimmunity." (PMID 37759563, 2023). "The LAT–PLC-γ1 pathway requires conditions to be just right, as both signaling deficiency and hyperactivity can lead to immunodeficiency." (PMID 36914891, 2023). "The finding that LAT-deficient patients, like many ZAP-70-deficient patients, present with immunodeficiency as well as autoimmunity raises questions concerning the intricate crosstalk that regulate T cell responses from TCR signaling hubs." (PMID 37313400, 2023). "Genetic defects for LAT and more recently for SLP-76 in humans have been reported to cause severe immunodeficiencies and defective T-cell signaling." (PMID 34295339, 2021). "While LAT-signalosome triggers mostly forward positive signaling, it has been hypothesized that immune disorders could be unleashed by the removal of negative feedback mechanism in TCR signaling associated to LAT rather than altered T cell development in the thymus." (PMID 24204825, 2013). "Decreased numbers of T cells are prone to lead to immunodeficiency and autoimmune diseases, and patients with JIA are likely to have decreased autoimmune function due to lack of LAT." (PMID 36362342, 2022).
Autoimmunity (12 papers, 2013 to 2025). The occurrence of an immune reaction against the organism's own cells or tissues. "The heterogeneity of disease resulting from LAT-deficiency has led some to distinguish LAT-dependent pathology due to immune hyper-activation from true autoimmunity." (PMID 34012443, 2021). "Point mutation of LAT at Y136, the PLCγ-1 binding site, causes massive lymphoproliferation and autoimmunity in mice." (PMID 24204825, 2013). "LatY136F mice have a loss of function mutation in the linker for activation of T cells (LAT) adaptor and develop defective LAT signalosome pathology (DLSP), an autoimmune disorder with type 2 inflammation." (PMID 40785550, 2025). "Here, we show that LAT is redox-regulated, having an impact on thymic selection, peripheral T cell populations, and autoimmunity." (PMID 38671946, 2024). "When comparing the clinical phenotype with other CID due to TCR signaling defects, LAT and ZAP70 deficiency present with the strongest tendency towards autoimmunity." (PMID 38112969, 2023). "Mutant mice in which tyrosine at position 136 of LAT is replaced with phenylalanine (LatY136F mice) develop a lymphoproliferative disorder involving CD4+ T cell effectors that trigger systemic autoimmunity." (PMID 33125054, 2021). "Conversely, mutations or deletions of LAT in mature post-thymic T cells altered but did not completely impair T cell functions, and even led to autoimmunity and aberrant lymphoproliferation, implicating LAT in not only T cell activation but also regulation." (PMID 34012443, 2021). "This identifies LAT-dependent modules that could account for the onset of LAT-dependent autoimmunity and highlights alternative signaling routes (e.g. the “GEF & GAPS” hub; see the discussion)." (PMID 24204825, 2013). "Notably, ZAP70‐deficient mice, as well as LAT‐mutated mice (the latter discussed in more detail later in this review), reveal a causal link between impaired TCR signaling associated with immune dysregulation and autoimmunity." (PMID 34923645, 2022).
latent infection (12 papers, 2012 to 2021). "HSV latency-associated transcripts (LATs) are associated with the latent infection, but LAT transcriptional regulation was seldom reported." (PMID 32231745, 2020). "Because it is a hallmark of authentic latent infection, increased LAT expression validates our in vitro model of quiescence." (PMID 29073268, 2017). "Among them, six miRNAs, miR-H2-H5, -H7, and -H8, are within the second LAT exon and are typically expressed during latent infection." (PMID 33546553, 2021). "During its latent infection, HSV-1 produces only a miRNA precursor called LAT, which encodes six distinct miRNAs." (PMID 33546553, 2021). "The deletion of both LAP2 and LAP1 eliminated the ability to detect LAT in acute and latent infections." (PMID 32231745, 2020). "Overall, the impact of deleting the 5′ end of the LAT locus on HSV-1 infection of human skin was much more dramatic than has been reported in latent infection models." (PMID 33370402, 2020). "These seemingly contradictory observations suggest that first, UL7-MU is capable of entering neurons during latent infection, and second, the mutated UL7 does block transcription of LAT mRNA from the viral genome in neurons to some extent." (PMID 27618986, 2016). "The establishment of latency in LD and HD B6-Rag mice showed characteristic changes in lytic and LAT gene expression similar to what has been reported for immunocompetent wt mice transitioning from acute to latent infection." (PMID 25760441, 2015). "In these studies, by using the LAT promoter, we have shown high expression of each gene during both primary and latent infections." (PMID 24475315, 2014). "In 1997, two studies demonstrated the increased abundance of lytic gene transcripts during acute and latent infection of murine TG with a LAT deletion mutant." (PMID 22150699, 2012). "In these experiments, the levels of LAT expression were found to correlate with viral DNA loads revealing a deficit in the establishment of latent infection by the ICP0 mutant." (PMID 22150699, 2012). "During latent infection, the only abundant viral gene product is a non-coding RNA, the LAT." (PMID 33546553, 2021). "The deletion of LAP2 alone diminished levels of LAT expression in both acute and latent infections." (PMID 32231745, 2020). "The mechanisms of LAT-mediated latent infection have been proposed as many hypotheses, but it is still unclear." (PMID 32231745, 2020). "Since the LAT locus is important for both lytic and latent infection, understanding its functions in human skin is relevant for vaccine design and could be used for identifying novel antiviral targets." (PMID 33370402, 2020). "During latent infection, when repression of lytic gene expression (or certain host factors) is beneficial to the virus, removal of the block to miRNA biogenesis combined with high transcription of the LAT locus permits strong expression of latent miRNAs." (PMID 30755517, 2019). "To better understand the significance of our identification of the novel LAT TRSs and TFs, we integrated reported hypothesis and our novel findings, and proposed possible mechanisms for the initiation and maintenance of HSV latent infection." (PMID 32231745, 2020). "Similar to the LAT gene of HSV, pag1 plays an important role during HzNV-1 latent infection." (PMID 30546025, 2018). "LAT expression is not an absolute indication of latency establishment, as LAT-defective HSV-1 can establish latent infection in mice." (PMID 24567732, 2014).
lymphoproliferative disorder (10 papers, 2011 to 2025). "It has been shown that mice homozygous for a single tyrosine mutation in LAT exhibited an early block in T cell maturation but later developed a polyclonal lymphoproliferative disorder that produced high amounts of Th2 cytokines." (PMID 23360572, 2013). "Not only did these LAT-deficient CD4+ T cells respond to TCR engagement with Lck and ZAP70 phosphorylation of their targets including SLP76, they fully recapitulated the lymphoproliferative disorders associated with constitutive LAT mutation." (PMID 23189081, 2012). "Unexpectedly, induced deletion of LAT or expression of LATY136F in peripheral T cells leads to the same lymphoproliferative syndrome as when LAT is mutated in thymocytes." (PMID 21966541, 2011). "While our study indicated the importance of the LAT-PLCγ1 signaling pathway in Tfh differentiation, it remains to be determined whether this abnormal Tfh differentiation indeed causes the lymphoproliferative syndrome." (PMID 33912184, 2021). "However, two LAT-knockin (KI) strains of mice harboring point mutations in the four most distal tyrosines developed lymphoproliferative disorders involving helper T (TH) cells." (PMID 33042995, 2020). "Studies of LAT mutations in mouse models, where the COOH-terminal tyrosine residues of LAT are altered, have shown that defective LAT signaling can lead to lymphoproliferative disorders characterized by polyclonal T cells with increased Th2 cytokine production." (PMID 40469304, 2025). "A LAT-knockin (LAT-KI) strain of mice in which Tyr136 was mutated to phenylalanine (LATY136F) displays a severe but partial block in T cell maturation, but later develop a polyclonal lymphoproliferative disorder involving CD4+ T cells producing massive amounts of T helper type 2 (TH2) cytokines." (PMID 36569841, 2022). "Analyses of mice with deletion of LAT or expression of mutant LATY136F in peripheral T cells revealed surprising findings; these mice developed the same lymphoproliferative disorder as when LATY136F was introduced in the germline, resulting in thymocytes (and T cells) expressing LATY136F protein." (PMID 21966541, 2011).
autoimmune disease (7 papers, 2021 to 2025). A disorder resulting from loss of function or tissue destruction of an organ or multiple organs, arising from humoral or cellular immune responses of the individual to their own tissue constituents. "At the LAT locus, we found that lead SNP rs4788115-A was associated with reductions in both LAT expression and endometrial cancer risk while increasing autoimmune disease (type 1 diabetes) risk." (PMID 40428397, 2025). "Consistent with findings in Zap70 mutants, the signaling defects in at least one ZAP70 substrate, LAT, can also lead to autoimmune disease." (PMID 34923645, 2022). "Consistent with the findings in Zap70 mutants, the signaling defects in ZAP70 substrate, LAT, can also lead to autoimmune diseases." (PMID 34923645, 2022). "Taken together, our experiments indicate that LAT is redox-regulated, interacting with NCF1/NOX2 complexes, and may therefore be a key target for understanding and intervening in the treatment of RA and other autoimmune diseases." (PMID 38671946, 2024). "Positive and negative functions were solely assigned to the LAT and CD5 signalosomes, respectively, whereas the CD6 signalosome conveys antithetical functions with implications for autoimmune diseases." (PMID 33125054, 2021).
COVID-19 (7 papers, 2021 to 2024). A disease caused by infection with severe acute respiratory syndrome coronavirus 2. "Notably, a proteomic blood profiling study reported a significant association between LAT expression and COVID-19 susceptibility." (PMID 38181733, 2024). "From the “control vs case” analysis, 71 proteins on the neurology panel were identified to be perturbed in COVID-19, with LAT identified to be the most perturbed in this analysis (logFC = − 3.9, p-value = 4.46e−22)." (PMID 33737684, 2021). "This suggests that the remaining CpGs (annotated in genes such as CCDC61, CD38, FAM38A, LAT, TREX1 or NFAT5, among others) differentially contribute to similarities between COVID-19 progression and SADs, some of them regulating the activation and differentiation of T and B lymphocytes." (PMID 35933486, 2022). "In general, FCER1g, ICAM1, LAT, LCN2, and PLAU may be the main immune genes that are regulated by COVID-19 to induce olf and neurological dysfunction." (PMID 34504502, 2021). "LAT, VAV1, ZAP70, and CARD11, as the key components of T-cell receptor, exhibited a significant decrease with severity in COVID-19, negative with G004246 and CATG00000032642.1." (PMID 35573725, 2022).
clear cell renal cell carcinoma (5 papers, 2019 to 2021). "However, this trend was the opposite in another study, where overexpression of LAT was associated with poorer overall survival among patients with clear cell renal cell carcinoma." (PMID 34885177, 2021). "Methylated hub genes, including HOXD3, LAT, and NFE2L3, were proved to be a novel prognostic indicators in clear cell renal cell carcinoma." (PMID 32296463, 2020). "For the survival analysis, we found that hypomethylation and over-expression of LAT and NFE2L3 were correlated with poor survival, while hypermethylation and low-expression HOXD3 was correlated with poor survival of clear cell renal cell carcinoma patients." (PMID 31777602, 2019).
Sepsis (5 papers, 2014 to 2025). Sepsis is defined as life-threatening organ dysfunction caused by a dysregulated host response to infection. "In the GSE65682 dataset, CD3E (AUC:0.9509), HLA-DRA (AUC:0.974), IL2RB (AUC:0.9931), ITK (AUC:0.9727) and LAT (AUC:0.9575) showed good diagnostic efficiency in distinguishing sepsis patients from healthy controls." (PMID 38166628, 2024). "Additionally, five hub immune-related genes (CD3E, HLA-DRA, IL2RB, ITK and LAT) were identified from the protein–protein interaction network, and sepsis patients with higher expression of hub genes had a better prognosis." (PMID 38166628, 2024). "Importantly, αIIb, clathrin and LAT expression were similar between healthy donors and sepsis patients." (PMID 36194487, 2022). "The acute phosphorylation/activation of ZAP-70, LAT, Erk or Akt in response to stimulation with immobilised or soluble CD3 and CD28 mAb was indistinguishable between control and any of the SIRS/sepsis groups." (PMID 25541945, 2014).